HDAC3 (histone deacetylase 3)
Diseases named in the same sentence as HDAC3 in open-access papers (continued):
Sharing a sentence is not in itself a finding about the gene and the disease.
tumor (continued). "Loss of tumor suppression in mice fed with SFN on alternating days might be related to the inability to sustain high enough SFN metabolite levels for effective HDAC3 inhibition." (PMID 26388957, 2015). "HDAC3, as a pivotal epigenetic regulator, plays a multifaceted role in modulating the tumor microenvironment and immune responses, making it a promising target for immunotherapy sensitization." (PMID 40006729, 2025). "In CRC, CBX4 acts as a tumor suppressor by interacting with histone deacetylase 3 (HDAC3) to repress the expression of the (runt-related transcription factor 2) RUNX2 gene, which activity promotes metastasis in CRC cell lines and mice model." (PMID 40175347, 2025). "RHOA lactylation at K118 (activation) and K162 (stabilization) orchestrated by the PCAF/HDAC3 enzymatic axis, enables constitutive oncogenic signaling to fuel tumor progression." (PMID 41291745, 2025). "In mouse models of peripheral T-cell lymphoma (PTCL), drugs that specifically inhibit HDAC3 are employed to enhance the efficacy of anti-tumor therapies." (PMID 40006729, 2025). "But, on the other hand, there is evidence that inhibiting HDAC3 expression will help restore or enhance the anti-tumor immune function of CD8+ T cells." (PMID 40006729, 2025). "Future research should concentrate on elucidating the molecular mechanisms by which HDAC3 inhibitors (HDAC3i) affect tumor and immune cells." (PMID 40006729, 2025). "Evidence also found that in tumor cells with HDAC3 knockout, the expression of CXCL8 was significantly upregulated." (PMID 40573881, 2025). "In malignancies, HDAC3 regulates multiple signaling pathways, influencing tumor initiation and progression." (PMID 40936898, 2025). "On the other hand, HDAC3 can induce immune cell dysfunction through multiple signaling pathways, thereby impairing the anti-tumor immune response." (PMID 40006729, 2025). "The rationale behind targeting HDAC3 for tumor immunotherapy sensitization lies in its ability to modulate the immune landscape." (PMID 40006729, 2025). "Given that increased activity of STAT3, NF-κB, EZH2, and HDAC3 has also been reported in other tumors, it will be interesting to investigate the role of IκBζ in additional tumor entities." (PMID 40562773, 2025). "A novel selective HDAC3 inhibitor, HQ-30, has been demonstrated to enhance anti-tumor immune responses by regulating PD-L1 expression." (PMID 40006729, 2025). "One of the primary mechanisms by which HDAC3 facilitates tumor growth is by repressing the expression of genes involved in tumor suppression, apoptosis, and cell cycle control." (PMID 40006729, 2025). "Restoring STING expression by inhibiting HDAC3 with RGFP-966 leads to reduced tumor growth and enhanced cell apoptosis." (PMID 39949780, 2025). "We further explored the impact of targeting HDAC3 in the tumor micro-environment using an AML-BMSC co-culture xenograft model." (PMID 40623992, 2025). "In an in vitro experiment, the knockout of HDAC3 using CRISPR/Cas9 resulted in increased DNA damage in irradiated tumor cells, thereby reversing the resistance of rhabdomyosarcoma (RMS) to radiotherapy and exerting a radiosensitization effect." (PMID 40006729, 2025). "The application of HDAC3 inhibitors as immunotherapy sensitizers in combination with immunotherapy presents a promising strategy for tumor treatment." (PMID 40006729, 2025). "Inhibition of HDAC3 can promote the expression of genes related to antigen presentation and immune recognition, thereby enhancing the visibility of tumor cells to the immune system." (PMID 40006729, 2025).
tumor (continued). "It is therefore of high clinical value to maximize the anti-tumor effects of HDAC3 inhibition in the broader population of DLBCL patients, in addition to the subset of cases harboring CREBBP mutations." (PMID 39117798, 2024). "Several studies have shown that Myc regulates the expression of the tumor-repressor miRNAs by recruiting HDAC3 and impairs their activity through altered acetylation." (PMID 39409979, 2024). "HDAC3 inhibition, viral mimicry and cell-intrinsic IFN responses have been associated with enhanced anti-tumor immunity and synergy with immunotherapy such as checkpoint inhibitors." (PMID 39117798, 2024). "Combining HDAC3 inhibition with PD-L1 blockade further results in synergistic effects, suggesting integrated anti-tumor immunomodulating effects of epigenetic agents and immunotherapy." (PMID 39117798, 2024). "We also unveil a role of HDAC3 in the in vivo tumor growth of FP-RMS cells showing that HDAC3 depletion strongly affects both the onset and growth of tumor masses." (PMID 39107280, 2024). "Histological examination for animal tumor tissues revealed high expression levels of E-cadherin phosphorylation in the groups of Honokiol and gene silencing HDAC3." (PMID 34973135, 2023). "HDAC3 is known to play a role in cell proliferation, apoptosis, transcriptional repression and negatively regulating tumor-induced angiogenic potential." (PMID 37415101, 2023). "In terms of the mechanism, SETD5 is proposed to act as a tumor driver by inhibiting tumor suppressor gene transcription through H3K9 methylation via interacting with G9a/HDAC3 complex." (PMID 36875494, 2023). "The synergistic effect of HDAC3 inhibitors and PD-L1 blockade restores the ability of tumor-infiltrating lymphocytes to kill DLBCL cells in a major histocompatibility complex class I (MHCI) and MHCII-dependent manner." (PMID 36831561, 2023). "Clinical pathological analysis was performed to determine the relationship between HDAC3 and tumor progression." (PMID 34973135, 2023). "The effect of TQ, PIP, and SOR treatment on the expression of DNMT3B/HDAC3 genes and the tumor suppressor miRNA-29c was examined by RT- PCR." (PMID 36870998, 2023). "The methylation of C/EBPα prevents its interaction with the inhibitor histone deacetylase 3 (HDAC3) and reduces the formation of the C/EBPα-HDAC3 complex, which has an inhibitory effect on Cyclin D1, thereby promoting the proliferation of tumor cells." (PMID 36770809, 2023). "Intriguingly, a previously reported study has shown an upregulation of HDAC3 in tumor tissues of RCC." (PMID 36266728, 2022). "Epigenetic silencing is attenuated by HDAC3 depletion, suggesting a tumor-suppressive element of this deacetylase in the context of proteasome inhibition." (PMID 36846090, 2022). "Knockdown of HDAC3 reduces cell growth, migration, invasion, and cell viability, and increases apoptosis in GC lines and reduces tumor growth in xenograft models using GC cell lines." (PMID 36358890, 2022). "It was observed that tumor weight was much lighter and tumor growth speed was slower in the presence of sh-HDAC3, which was negated by oe-TGIF1 treatment." (PMID 35578338, 2022). "Taken together, these findings point to a pleiotropic function of HDAC3, in which the deacetylase mediates oncogenic or tumor-suppressive effects depending on the biological context and pharmacological agent used." (PMID 36846090, 2022). "Our experimental results showed that CDM elicited anti-tumor effects by inhibiting HDAC3-mediated deacetylation of FOXO1." (PMID 35126526, 2022). "At the same time, the results of immunohistochemical staining and Western blotting suggested a decline in the HDAC3 expression in the tumor tissues of CDM-treated mice, while FOXO1 acetylation level was increased in a dose-dependent manner." (PMID 35126526, 2022). "HDAC3 inhibition can also enhance PD-L1 expression in DC, and the combination therapy with anti-PD-L1 antibody enhances anti-tumor effects." (PMID 35163049, 2022).
tumor (continued). "In agreement, some studies clearly indicated that the magnitude of growth inhibition and apoptosis induced upon selective HDAC3 inhibition in tumour cells was relatively modest compared to the effects induced by Class I or pan-HDAC inhibitors." (PMID 35626663, 2022). "Further study, we explored the effects of targeting Rictor‐HDAC3 axis on the liver TICs and tumor growth in vivo." (PMID 35187863, 2022). "The results showed that blockade of glutamine uptake using V9302 combined mTORC1/2 inhibitor AZD2014 blocking the interaction between HDAC3 and GS not only significantly delayed the tumor growth but also resulted in partial or even complete tumor regression." (PMID 35187863, 2022). "The primary goals of this study were to investigate the potential roles of ZNF22 and HDAC3 as a histone deacetylase in regulating an increases in blood-tumor barrier (BTB) permeability and some of the possible molecular mechanisms associated with this effect." (PMID 36518188, 2022). "Concordantly, the results in our study showed that miR-195-5p was downregulated in RCC, while downregulation of miR-195-5p counterweighed the anti-tumor action of silencing HDAC3." (PMID 36266728, 2022). "For example, HDAC3 inhibitors synergize with PD-L1 blockade to enhance tumor regression by transcriptionally upregulating PD-L1 expression." (PMID 35646698, 2022). "To conclude, these findings offered evidence on the anti-tumor action of HDAC3 silencing by inhibiting malignant cellular properties of ESCC cells." (PMID 35578338, 2022). "Tumor tissues were fixed with formalin, embedded in paraffin, and stained with H&E and IHC to detect HDAC3 and FOXA1 expression." (PMID 34991620, 2022). "Conversely, treatment with CDM-H+oe-HDAC3 increased the number of tumor cells and reduced fibrous tissues formation." (PMID 35126526, 2022). "Collectively, the tumor suppressive activity of HDAC3 silencing was reproduced in vivo dependent on the miR-494/TGIF1/TGFβ axis." (PMID 35578338, 2022). "Although HDAC3 inhibition can enhance PD-L1 in the tumor, PD-L1 in dendritic cells is also suppressed." (PMID 35163049, 2022). "And HDAC3 expression was significantly related to tumor size, venous infiltration, TNM stage and Edmondson Steiner grading." (PMID 34335948, 2021). "In PDX models, HDAC3 inhibition with BRD3308 reduced tumor growth, and induced upregulation of BCL6 target genes and MHC-II expression in the setting of both CREBBP-mutant and CREBBP-WT diseases." (PMID 35071240, 2021). "HDAC3 is linked to the development of smoking-induced PDAC through regulation of the cytokine IL-6 and interactions between cancer cells and tumor promoting macrophages." (PMID 34685500, 2021). "According to this study, enhanced HDAC-3 gene expression was noted in CRC patients, being associated with a poor grade of tumor differentiation (G3)." (PMID 34441281, 2021). "RT-qPCR analysis data from HCC tissues and adjacent non-tumor tissues showed that HDAC3 is significantly upregulated in HCC tissues (P<0.05), which was consistent with the data from public dataset TCGA (P<0.05)." (PMID 34335948, 2021). "It has been pointed out that the accumulation of HDAC3 is directly related to the promotion of tumor occurrence and development." (PMID 34658308, 2021). "Using four genetically defined murine PDAC cells we analyzed how hydroxyurea and entinostat, a specific inhibitor of the class 1 HDACs HDAC1/HDAC2/HDAC3, affect this tumor type." (PMID 34685500, 2021). "Histone deacetylase (HDAC)-3 is a class I HDAC that is involved in tumor development, DM, inflammation, and cardiovascular and neurodegenerative diseases." (PMID 33736642, 2021). "The outcomes implied that down‐regulation of HDAC3 elevated miR‐495‐3p to suppress tumour growth in vivo through declining TRAF5." (PMID 33048450, 2020). "It is demonstrated that down-regulated HDAC3 or TGIF1 or up-regulated miR-296-3p is the restriction for tumor growth in nude mice." (PMID 33203425, 2020).
tumor (continued). "Our results therefore provide the preclinical rationale for clinical trials targeting HDAC3 in BMSCs to indirectly inhibit tumor cell growth, survival, and drug resistance in the BM milieu and thereby improve patient outcome." (PMID 31142847, 2020). "PD-L1 and c-Jun levels were significantly increased, while HDAC3 levels were significantly decreased in the cisplatin-resistant NSCLC tissues compared with the cisplatin-sensitive tumor tissues." (PMID 32024543, 2020). "Our results showed that downregulation of HDAC3 attenuated the increased colony formation and tumor-sphere formation capability induced by downregulation of USP38." (PMID 32404892, 2020). "Cytoplasmic expression of HDAC3 was further upregulated in the brain metastases compared with the matched primary tumours, while nuclear expression was downregulated." (PMID 32686908, 2020). "HDAC3 also appeared to have functional roles in promoting tumor cell proliferation and invasion in vitro, indicating the potential for HDAC3 to serve as a biomarker and therapeutic target for HBV-associated HCC." (PMID 31056726, 2019). "The tumor tissue lysates of CT26Flag−CAGE1 cells revealed the activation of mast cells based on the induction of interactions of FcεRIβ with HDAC3 and SOCS1." (PMID 31799196, 2019). "For example, condition medium derived from tumor cells increased the expression of several transcription factors in MC that influence allergic inflammation, such as Histone deacetylase-3 (HDAC3), SOCS1, and SNAIL, as well as increasing MC degranulation." (PMID 31052286, 2019). "Tumor tissue lysates of the CT26Flag−CAGE1 cells showed the interaction of FcεRIβ with HDAC3 and SOCS1." (PMID 31799196, 2019). "Our CRISPR studies of the HDAC targets of ENT suggest that HDAC3 is a key factor to eRMS cell-autonomous tumor cell survival." (PMID 31113472, 2019). "Prostate‐specific knockout of Hdac3 decreased Akt phosphorylation, alleviated the tumor burden, and ultimately prolonged survival of Pten knockout mice." (PMID 29523594, 2018). "Future studies will involve assessing KLF4 protein expression in mice tumors as well as the expression of HDAC2, HDAC3 and hTERT in the tumor tissues." (PMID 29899271, 2018). "HDAC3 inhibition significantly reduced tumor growth and decreased the expression of Ki67 in HCC xenograft tumors." (PMID 29540666, 2018). "Clinical data to support the tumour-promoting role of HDACs include the overexpression of HDAC3 in 30–50% of HCC cases, particularly in HBV related HCC." (PMID 29079534, 2017). "In conclusion, these data suggest that N25 has striking anti-tumor activity in part due to inhibition of HDAC3." (PMID 29088860, 2017). "Tumor-suppressor role of HDACs has also been noticed as overt HCC that occurred as a result of liver-specific knockdown of HDAC3." (PMID 28401148, 2017). "We evaluated the tissue microarrays, which contain clinically annotated genomic data from CCA samples, and found that HDAC3 protein was overexpressed in 47/127 CCA cases (37%), and was associated with tumor size." (PMID 28569784, 2017). "The decision to include sunitinib and vorinostat was based on our findings that PDGFRB and HDAC3/8 were overexpressed in our patient's tumor." (PMID 28993730, 2017). "SOCS1peptide prevented antigen from increasing β-hexosaminidase activity in tumor tissue and prevented antigen from increasing the expression of SOCS1 and HDAC3 in tumor tissue." (PMID 28968979, 2017). "Our study demonstrated that N25 has striking anti-tumor activity and was the first to show that HDACi induces autophagy through inhibiting HDAC3." (PMID 29088860, 2017). "SOCS1-KIR also prevented antigen from increasing the expression of SOCS1, HDAC3 and TGaseII and also prevented antigen from inducing an interaction of FcεRIβ with HDAC3 and Lyn in tumor tissue." (PMID 28968979, 2017).
tumor (continued). "In conclusion, N25 has obvious anti-tumor activity in vivo and in vitro and through inhibition of HDAC3." (PMID 29088860, 2017). "For example, nuclear HDAC3 expression was detected in 80.0% of patients with high tumor grade (> IIa), but only 36.7% in the low tumor grade group (≤ IIa), suggesting that nuclear HDAC3 plays an important role in tumor progression in PC patients." (PMID 26918727, 2016). "We previously revealed that HDAC3 is overexpressed in PC tissue, and increased HDAC3 can promote malignant tumor phenotypes." (PMID 26918727, 2016). "Among the changes driving this benign vs. tumor separation, we observed the downregulation of HDAC3 and Sirt2 as reported." (PMID 27863398, 2016). "Multivariate analysis shows that cytoplasmic CDH1 expression, nuclear HDAC3 expression, and tumor differentiation were independent prognostic factors for PC patients." (PMID 26918727, 2016). "Inversely, in non-invasive tumor cells miR-31 targets SOX4, EZH2 and HDAC3 by direct and indirect means to inhibit tumor cell invasion." (PMID 25644061, 2015). "Immunoblotting of tissue lysates from tumor and adjacent normal colon revealed that HDAC3 expression was reduced by SFN treatment in WT mice, but not in mice on the Nrf2−/+ background." (PMID 26388957, 2015). "We, therefore, propose that one underlying mechanism by which miR-31 suppresses tumor cell invasion is by directly targeting SOX4 and indirectly targeting EZH2 and HDAC3." (PMID 25644061, 2015). "The immunohistochemical staining of tumor tissues showed that the positive staining of HDAC3 in Ad-ZBP-89 group was less than that in the saline group." (PMID 25623232, 2015). "In EAC dataset (GSE13937), we found that SOX4 (P value = 0.003) and HDAC3 (P value = 0.042) were increased in tumor samples compared to adjacent normal tissues." (PMID 25644061, 2015). "Targeting the tumor microenvironment with HDAC3 selective inhibitors is another potentially innovative strategy." (PMID 24904826, 2014). "An example for a strongly anticorrelated, non-synonymous pair with a tumor-downregulated mRNA is HDAC3 and its antisense lncRNA transcript." (PMID 25264628, 2014). "We found HDAC3 expression in normal samples and strongly downregulated but detectable in tumor tissue samples." (PMID 25264628, 2014). "HDAC2 and HDAC3 are strongly expressed in subgroups of tumor with features of a more aggressive tumor type." (PMID 23627572, 2013). "Overall, we report data showing anti-tumor role for miR-100 in GBM, and reveal that regulation of miR-100 levels, plus SMRT/NCOR2 and associated downstream pathways (e.g. HDAC3) are potential therapeutic targets for GBM." (PMID 24244722, 2013). "In fact the papillary RCC, which were positive for HDAC3, tended to be of lower tumour stage in our cohort." (PMID 19099586, 2008). "Another rather unexpected finding was the reciprocal correlation of HDAC3 with tumour stage (pT-status)." (PMID 19099586, 2008). "An important role of class I HDACs, especially HDAC3, on cell proliferation has also been reported for other tumour entities, which again makes it an interesting therapy target." (PMID 18212746, 2008). "Overexpression of HDAC3 may facilitate tumor cell apoptosis and promote the release of factors such as IL-2 and IFN-γ by activating the CGAS-STING pathway." (PMID 40006729, 2025).